COL4A1 (collagen type IV alpha 1 chain)
Diseases named in the same sentence as COL4A1 in open-access papers (continued):
Sharing a sentence is not in itself a finding about the gene and the disease.
cerebral small vessel disease (23 papers, 2016 to 2025). Cerebral small vessel disease is the term currently used to pathological processes that affect the brain parenchymal circulation (arterioles, capillaries, and veins). "COL4A1‐related vasculopathies mutations are autosomal dominant disorders and are associated with a range of cerebral small vessel diseases due to their effect on basement membrane integrity." (PMID 41001161, 2025). "COL4A1 monogenic mutations are associated with cerebral small-vessel disease and other systemic manifestations." (PMID 37681221, 2023). "The present study identified a total of 22 patients with mutations in NOTCH3, HTRA1, and COL4A1, which are known to cause cerebral small vessel disease (SVD)." (PMID 37237429, 2023). "COL4A1 mutation related disorders are part of hereditary small vessel diseases and are characterized as cerebral small vessel diseases with diverse disease phenotypes that include porencephaly, stroke, glaucoma, and other angiopathies." (PMID 32653987, 2021). "SH2B3 (SH2B adaptor protein 3; dbGENE 10019) is involved in cytokine signaling pathways and COL4A1 (collagen type 4 alpha 1; dbGENE 1282) has also been implicated in cerebral small vessel disease." (PMID 26982883, 2016). "As a cerebral small vessel disease, COL4A1 related disorders cause familial vasculopathy and may present with ischemic as well as hemorrhagic stroke, in adult life with radiological features of leukoaraiosis and microbleeds." (PMID 32653987, 2021). "A recent study has proved that mutation located at the COL4A1 3′ UTR of the miR-29s binding site could cause human cerebral small vessel disease." (PMID 32637572, 2020). "For example, variants within a 7 bp region of the COL4A1 3′UTR (e.g. NM_001845.6:c.*31G > T) abolish a binding site for the miR-29 miRNA, leading to increased levels of COL4A1 mRNA and leading to cerebral small vessel disease." (PMID 40610610, 2025). "Pontine autosomal dominant microangiopathy and leukoencephalopathy (PADMAL) is a rare hereditary subtype of cerebral small vessel disease, caused by mutations in the 3′ untranslated region (UTR) of the COL4A1 (collagen type IV alpha 1 chain) gene." (PMID 35163523, 2022). "COL4A1-related disorders are characterized by a higher incidence of cerebral hemorrhage than other hereditary cerebral small vessel diseases." (PMID 33990551, 2021). "For patients carrying variants outside EGFr region, no potential pathogenic mutation were identified in several other genes known to be common causal of cerebral small-vessel disease or vascular dementia (HTRA1, TREX1, COL4A1, COL4A2, GLA, APP, and ITM2B) by targeted next-generation sequencing." (PMID 34335700, 2021). "Importantly, ICH was predominantly detected in the basal ganglia of 8MO Col4a1 mutant mice, which contains perforating vessels that are commonly compromised in cerebral small vessel disease." (PMID 29895609, 2018). "Collagen isoforms COL4A1 and COL4A2, defined in a GWAS analysis of cerebral small vessel disease as mainly expressed in the brain endothelial cells." (PMID 35008650, 2021).
breast carcinoma (22 papers, 2008 to 2025). "Among them, overexpression of COL4A1 has been linked to the proliferation of breast cancer cells and has been identified as a prognostic biomarker for intrahepatic cholangiocarcinoma." (PMID 38907304, 2024). "Using gene co-expression analysis, we showed that P4HA2 was associated with expression of Col1A1, Col3A1, and Col4A1 during breast cancer development and progression." (PMID 24383403, 2014). "The results showed that COL4A1 is associated with breast cancer prognosis." (PMID 35646090, 2022). "For instance, COL4A1 has been reported to facilitate tumor cell invasion, migration, and angiogenesis in multiple cancer types, including gastric, colorectal, and breast cancers." (PMID 40087784, 2025). "MMP1-3 secretion in breast cancer cells is stimulated by the activation of the PRL/PAK1 signaling pathway via COL4A1." (PMID 38004422, 2023). "Some studies have analyzed 206 surgical pathology specimens from breast cancer and adjacent tissues using immunohistochemical staining with antibodies specific to COL4A1 and evaluated the correlation between clinical results and the IHC score of COL4A1." (PMID 35646090, 2022). "Research has indicated that the col4a1 knockdown decreases cell viability and suppresses cell cycle progression in breast cancer cells." (PMID 34956338, 2021). "COL4A1 was expressed at higher levels in the breast cancer tissues compared to the 206 pairs of adjacent normal tissue (P < 0.0001)." (PMID 32565804, 2020). "The breast cancer mRNA database was searched to analyse the expression of COL4A1 mRNA in BC patients who received neoadjuvant chemotherapy and the effects on their overall survival." (PMID 32565804, 2020). "We analysed 206 surgical specimens from patients with breast cancer and adjacent normal tissue using IHC staining with a specific antibody against COL4A1 and evaluated the correlation between the clinical outcomes and the IHC scores of COL4A1." (PMID 32565804, 2020). "Cluster 110 contains genes that have previously been associated with chemotaxis and invasion of breast cancer cell lines (SLIT2, RECK), as well as genes related to the extracellular matrix (ECM2, COL4A1)." (PMID 18498629, 2008). "We showed that miR-190a-3p, a key regulator of gene expression and pathways important in breast cancer, is potentially involved in the regulation of COL4A1, MAPK3, PIK3CG, and PIK3R1, all of which are integral to pathways associated with breast cancer progression." (PMID 39850811, 2024). "In addition, COL3A1, COL4A1, COL5A1, and COL15A1 are associated with immune infiltration in head and neck squamous cell carcinoma, breast cancer, mesothelioma, and other tumors." (PMID 34691289, 2021). "Overexpressed COL4A1 contributes to the proliferation and migration of breast cancer cells." (PMID 32746865, 2020). "In breast cancer, COL4A1 induced MMP-9 expression by activating Src phosphorylation." (PMID 32746865, 2020). "And COL4A1 knockdown led to cell viability reduction and cell cycle arrest in breast cancer cells." (PMID 29921304, 2018). "Interestingly, COL4A1 was also upregulated in breast cancer and ovarian cancer like RUNX1." (PMID 32746865, 2020). "Here, we showed that expression of P4HA2 and collagen genes (Col1A1, Col3A1, and Col4A1) is significantly correlated during breast cancer development and progression, and that increased mRNA levels of P4HA2 are associated with poor prognosis in breast cancer patients." (PMID 24383403, 2014). "Of the two dbVar whole-gene DUPs, the COL4A2 339,611 bp CG, with breakpoints disrupting COL4A1 and NAXD, observed in a single African patient is defined as a PP-SV, as COL4A2 indicating oncogenic behaviour in gastric and breast cancers." (PMID 38947031, 2024). "The correlation between COL4A1 expression and long-term OS and RFS in breast cancer patients was further investigated by Kaplan–Meier analysis." (PMID 35646090, 2022).
breast carcinoma (continued). "We further investigated the correlation between COL4A1 expression and long-term OS and RFS in patients with breast cancer via Kaplan–Meier analysis." (PMID 32565804, 2020). "Specifically, the identification of miRNAs such as miR-129, miR-19a-3p, and miR-30d-5p, as well as proteins like COL4A1, MAPK3, PIK3CG, and mTOR, provides valuable insights into the molecular mechanisms underpinning aggressive breast cancer subtypes, such as TNBC." (PMID 39850811, 2024). "In breast cancer cell line MCF-7 resistant to Vincristine (Vin), Pac, Docetaxel (Doc) and Dox, authors observed overexpression of six COL genes with the most abundant expression of COL4A1." (PMID 24804215, 2014).
porencephaly (21 papers, 2011 to 2025). Porencephaly is characterized by a circumscribed intracerebral cavity of variable size that may be bordered by abnormal polymicrogyric gray matter. "Large scale studies validated COL4A1 mutations as frequent causes of porencephaly and schizencephaly and COL4A1 and COL4A2 as frequent causes of prenatal hemorrhagic or ischemic cerebral lesions." (PMID 41311701, 2025). "This multimodal imaging modality also detected porencephaly and schizencephaly, two radiological findings associated with Gould syndrome, in Col4a1 mutant mice." (PMID 41311701, 2025). "It is believed that mutations in the COL4A1 gene, which induce brain small-vessel disease with haemorrhage, are the source of porencephaly in families." (PMID 39416588, 2024). "Features suggestive of COL4A1 mutations include severe and/or multifocal hemorrhagic or ischemic-hemorrhagic cerebral lesions, especially when such injuries are associated with porencephaly." (PMID 38978838, 2024). "With the generation of mouse models of COL4A1-related disorder,14,15COL4A1 mutations were reported as the primary cause of hereditary porencephaly with an autosomal dominant inheritance." (PMID 32042920, 2020). "Previous identification of COL4A1 mutations in patients with porencephaly led us to perform candidate gene mutation analysis on a large pedigree presenting with autosomal dominant porencephaly with reduced penetrance." (PMID 24001601, 2014). "COL4A1 mutations were initially discovered in humans as a genetic cause of porencephaly and cSVD." (PMID 41311701, 2025). "COL4A1 was already described as associated with a wide spectrum of small-vessel brain disease including porencephaly, variably associated with eye defects and systemic findings (kidney involvement, muscle cramps, cerebral aneurysms, Raynaud phenomenon, cardiac arrhythmia, and hemolytic anemia)." (PMID 39654947, 2024). "Notably, COL4A1 appears to be an important genetic cause of porencephaly – a condition usually diagnosed in infants and characterized by large cerebral cystic cavities that communicate with the ventricles." (PMID 21625620, 2011). "Other types of porencephaly show a similar spectrum, but are caused by mutations of COL4A1 or segment deletions of chromosome 13, which affect both the COL4A2 and COL4A1 genes." (PMID 31331924, 2019). "Mutations of COL4A1 have been shown to cause ICH and porencephaly both in mice and humans." (PMID 33920939, 2021). "In addition, with a high de novo mutation rate of 40%, 21 COL4A1 (12 of them novel) and 3 COL4A2 pathogenic mutations were identified, mostly in children with porencephaly or other patterns of parenchymal hemorrhage." (PMID 31484286, 2019). "We hypothesized that epilepsy could be a manifestation of disease even in patients in whom porencephaly is not evident and aimed to characterize the phenotypes associated with COL4A1/COL4A2 mutations, seeking genotype–phenotype correlation." (PMID 30413629, 2018). "Compared to disease caused by variants in the coding regions of COL4A1 and COL4A2, PADMAL has a later age at onset and does not lead to cerebral hemorrhages, or porencephaly." (PMID 36786861, 2023).
cerebrovascular disease (18 papers, 2011 to 2025). "COL4A1 encodes type IV collagen alpha protein, which is involved in the formation of the extracellular matrix and whose mutation can lead to cerebrovascular disease or muscle defects." (PMID 40386063, 2025). "Mice with Col4a1 missense mutations develop anterior segment dysgenesis, renal defects and cerebrovascular disease by 3 months of age." (PMID 39216230, 2024). "In humans, mutations in type IV collagen are known to cause dominantly inherited cerebrovascular disease; a Pro-to-Leu missense change in COL4A1 has been identified in a patient with sporadic cerebral hemorrhage." (PMID 29440357, 2018). "In addition to the high prevalence of cerebrovascular disease in patients with COL4A1 mutations, myopathy has been reported in over one-third of cases." (PMID 29895609, 2018). "Interestingly, six families with COL4A1 mutations and cerebrovascular disease also had muscle cramps and CK elevation." (PMID 21625620, 2011). "Interestingly and importantly, treating adult mice for 1 month with PBA reduced total ICH, providing strong evidence that targeting ER stress using chemical chaperones has efficacy as a treatment for pre-existing ICH and COL4A1-associated cerebrovascular disease." (PMID 30351356, 2019). "Here we show that, in addition to increased risk for cerebrovascular disease (and other multi-systemic complications), patients with COL4A1 or COL4A2 mutations should be carefully monitored for progressive retinal neovascularization that could lead to sudden blindness." (PMID 26813606, 2016). "Mutations in humans can also lead to decreased extracellular COL4A1 which contributes to sporadic cerebrovascular diseases and intracranial hemorrhage." (PMID 38331745, 2024). "These genes encode major basement membrane collagen proteins COL4A1 and COL4A2, and their mutations cause cerebrovascular diseases." (PMID 37958635, 2023). "We found that genes related to cerebrovascular diseases, such as COL4A1, COL4A2, VCAN and APOE were significantly enriched in the cerebrovascular ECM network." (PMID 33730931, 2021). "The COL4A1 and COL4A2 mutations were important causes of cerebrovascular disease with a high mutation detection rate in porencephaly and childhood cerebral hemorrhage, and a relatively high rate of de novo mutations." (PMID 31484286, 2019). "COL4A1 and COL4A2 mutations cause a multisystem disorder characterized by the presence of cerebrovascular disease with variable ocular, renal and muscular involvement." (PMID 29895609, 2018). "Mutations in COL4A1 and COL4A2 cause a multisystemic disorder that leads to cerebrovascular disease, eye defects and muscular dystrophy." (PMID 26839400, 2016). "COL4A1, and COL4A2 are highly conserved across species and dominant-negative mutations in these genes are pleiotropic and contribute to a broad spectrum of disorders including myopathy, glaucoma, and cerebrovascular disease." (PMID 33918807, 2021). "The identification of rare mutations in sporadic haemorrhaging, and that common COL4A2 variants are a risk factor for deep ICH and white matter hyperintensities in the general population, underscore an important role for COL4A1/COL4A2 in common cerebrovascular disease and ICH." (PMID 30351356, 2019). "COL4A1 and COL4A2 mutations have been reported in a broad spectrum of disorders, including myopathy, glaucoma, cerebrovascular disease, and renal, ophthalmological, cardiac, and muscular abnormalities, which were collectively termed “COL4A1 and COL4A2 mutation-related disorders”." (PMID 31484286, 2019). "Cerebrovascular disease is a particularly devastating consequence of COL4A1 mutations, and we have previously demonstrated that ICH severity in Col4a1+/Δex41 mice increases with age and is exacerbated by environmental factors, such as birth trauma, exercise and anticoagulants." (PMID 29895609, 2018).
cerebrovascular disease (continued). "Moreover, obligate carriers did not exhibit any signs of subclinical cerebrovascular disease, in contrast to the vascular abnormalities observed using MRI in almost 100% of asymptomatic carriers of COL4A1 mutations." (PMID 24001601, 2014). "Despite a growing recognition for the roles of COL4A1 and COL4A2 mutations in the etiology of cerebrovascular disease and myopathy, there are currently no targeted therapeutic interventions." (PMID 29895609, 2018).
glioma (18 papers, 2009 to 2025). A benign or malignant brain and spinal cord tumor that arises from glial cells (astrocytes, oligodendrocytes, ependymal cells). "By comparing the expression level in different histological types of gliomas, COL4A1 and COL4A2 were better predictors of glioblastoma (AUC = 0.918 and 0.9), followed by COL4A3 and COL4A4 (AUC = 0.67 and 0.746)." (PMID 40351420, 2025). "Other studies have indicated that METTL3 is downregulated in glioma tissues and regulates U251 cell proliferation and apoptosis by targeting COL4A1 and HSP9, potential therapeutic targets of glioma." (PMID 37189411, 2023). "In lower-grade glioma, COL3A1, COL4A1, and COL5A1 are associated with patient prognosis and tumor progression." (PMID 34691289, 2021). "Col4a1 has been shown to be over-expressed in glioma, and our current study showed that it was regulated by hsa-miR-524-5p and hsa-miR-628-5p." (PMID 24194606, 2013). "However, OV demonstrated a higher collagen formation score than glioma, and correspondingly, had a uniquely heightened abundance of E09-veins-COL4A1." (PMID 39345334, 2024). "Furthermore, in gliomas, collagen genes, including COL4A1, are involved in immune infiltration and epithelial–mesenchymal transition." (PMID 35455650, 2022). "The elevated expression of COL4A1 was correlated with low survival rates of patients with low-grade glioma, pancreatic adenocarcinoma, skin cutaneous melanoma, and stomach adenocarcinoma, thus suggesting its potential use as a biomarker for the poor prognosis of these tumors." (PMID 35455650, 2022). "The down-regulation of two protective miRNAs may further increase the expression of Col4a1 to promote the progression of glioma." (PMID 24194606, 2013). "In TCGA, GEO (GSE50161, GES7696, GES4290) and CGGA (mRNAseq_325) databases, we found the COL4A1, COL4A2 and COL4A6 expression were significantly increased in glioma tissues." (PMID 40351420, 2025). "We found the high expressions in COL4A1 and COL4A2 were positively related to a worse prognosis of glioma patient, while, in COL4A3 and COL4A4 were predicted to a better prognosis." (PMID 40351420, 2025). "The further analysis showed that COL4A1 and COL4A2 had similar upregulated expression levels in glioma tumor tissues." (PMID 40351420, 2025). "It indicated the COL4A1-2 were corelated to a worse prognosis, and COL4A3-4 predicted a better outcome in glioma." (PMID 40351420, 2025). "By using Oncomine databases, we found that the expression of COL4A1 to COL4A6 was closely related to brain and CNS cancer." (PMID 40351420, 2025). "Higher expression of COL1A1, COL1A2, COL3A1, COL4A1, COL4A2, and COL5A2 was negatively correlated with the prognosis of glioma patients." (PMID 38969910, 2024). "Next, we interrogated the glioma cohorts from TCGA and CGGA databases to further examine the expression and correlation characteristics of RUNX1, FOSL2, FN1, COL4A1, and LUM in GBM tumorigenesis." (PMID 38286983, 2024). "In a recent study, the collagen molecules COL4A1 and COL3A1 were proved to be essential for the development of glioma." (PMID 34034744, 2021). "On the CGGA website (mRNAseq_325), collagen genes (COL1A1, COL1A2, COL3A1, COL4A1, COL4A2, and COL5A2) in WHO grades II, III, and IV glioma samples were analyzed to explore the expression levels of these genes." (PMID 34034744, 2021). "Then, six collagen genes (COL1A1, COL1A2, COL3A1, COL4A1, COL4A2, and COL5A2) were selected for further validation in Oncomine, TCGA (The Cancer Genome Atlas), and CGGA (Chinese Glioma Genome Atlas) database." (PMID 34034744, 2021). "These genes, EGFR, COL4A1, and CDK4 all shared the ‘pathways to cancer’ annotation; and EGFR and COL4A1 were shown to be involved specific cancers such as glioma, melanoma, lung cancer, bladder cancer, and pancreatic cancer." (PMID 23737970, 2013).